INS (insulin)
Diseases named in the same sentence as INS in open-access papers (continued):
Sharing a sentence is not in itself a finding about the gene and the disease.
type 1 diabetes (continued). "For patients with type 1 diabetes or insulin-dependent type 2 diabetes, maintaining basal insulin is essential to prevent diabetic ketoacidosis and limit protein loss during periods of reduced caloric intake and perioperative stress." (PMID 39199594, 2024). "The current treatment of diabetes type I involves injection of insulin and patients are supposed to inject or wear an insulin pump subcutaneously." (PMID 38338467, 2024). "Blind spots prevail in the unmet needs for type 1 diabetes (T1D), a chronic autoimmune condition where individuals are unable to produce insulin, thereby dependent on lifelong insulin therapy and blood glucose management." (PMID 38905318, 2024). "Type 1 diabetes is an autoimmune disorder where the immune system attacks pancreatic beta cells, reducing insulin production." (PMID 39335472, 2024). "Long-term insulin irregularity leads to complications in several organs for a large proportion of individuals with type 1 diabetes." (PMID 39103720, 2024). "Leonard Thompson was the first patient with type 1 diabetes (T1D) to receive the first insulin dose to control glucose levels, marking an extremely important event that would dramatically change the prognosis of future patients with insulinopenic diabetes." (PMID 39200316, 2024). "This research demonstrates that alongside its glycemic benefits, use of a fully closed-loop insulin delivery system had significant quality-of-life benefits in adults with type 1 diabetes and suboptimal glucose outcomes." (PMID 38426909, 2024). "Type 1 diabetes mellitus (T1D) is a complex autoimmune disorder characterized by the progressive destruction of insulin-producing pancreatic beta cells." (PMID 39123252, 2024). "In NOD mice and later in humans, an active role was ascribed to beta cells in the pathophysiology of type 1 diabetes, via disruption of protein folding and consequent defects on insulin secretion and triggering of ER stress." (PMID 38864887, 2024). "Type 1 diabetes is believed to be an autoimmune condition, characterized by destruction of insulin-producing cells, due to the detrimental inflammation in pancreas." (PMID 38166933, 2024). "Scoring adults with type 1 diabetes based on three formulae to estimate insulin sensitivity matters, as the lowest quartile of each score was associated with CAD." (PMID 38702680, 2024). "For instance, technological advancements, including continuous glucose monitoring biosensors and insulin pumps, now benefit numerous individuals with type 1 diabetes." (PMID 39686207, 2024). "The omission of insulin therapy, often in the setting of psychological and socioeconomic factors, is a major cause of DKA, particularly among adults with type 1 diabetes living in socioeconomically deprived areas." (PMID 38907161, 2024). "Intake of low-dose ABA was shown to improve glycemic control and reduce the dose of insulin required to reduce blood glucose in murine models of type 1 diabetes." (PMID 39796447, 2024). "We present a rare case of insulin-induced amyloidosis or amyloidoma that slowly developed at a satellite location distant from the insulin pump site that required surgical excision in a patient with type 1 diabetes." (PMID 39081432, 2024). "Although high doses of STZ severely impair insulin secretion, similar to type 1 diabetes, low doses of STZ are known to cause mild impairment of insulin secretion, consistent with T2DM." (PMID 38952685, 2024). "Type 1 diabetes mellitus (T1D) is a chronic disease characterized by immune-mediated destruction of pancreatic beta cells, which leads to a progressive decrease in insulin secretion." (PMID 38790009, 2024). "New technologic approaches for both glucose monitoring and insulin delivery have been developed to improve strategies for Type 1 diabetes management." (PMID 38831294, 2024). "In type 1 diabetes (T1D), T-cells of the immune system selectively destroy the insulin-producing β-cells." (PMID 38161208, 2024).
type 1 diabetes (continued). "Type 1 diabetes (T1D) is a chronic autoimmune disorder characterized by the destruction of insulin-producing beta cells in the pancreas." (PMID 38347569, 2024). "We have previously shown that C-peptide, which is produced when proinsulin is converted to insulin, is an important antigen in human type 1 diabetes (T1D)." (PMID 39530093, 2024). "Type 1 diabetes mellitus (T1DM) is a chronic disease that requires insulin treatment due to the destruction of pancreatic beta-cells and can affect bone and skeletal health." (PMID 38872156, 2024). "The use of the IP route for type 1 diabetes treatment was made possible by the development of programmable implantable pumps that deliver insulin through an IP catheter." (PMID 39065641, 2024). "Type 1 diabetes (T1D), usually diagnosed during childhood, results from the destruction of insulin-producing pancreatic β-cells." (PMID 40302965, 2024). "Type 1 diabetes (T1D) is the most common type in the pediatric population; it results from autoimmune destruction of the pancreatic islet β cells that leads to a deficiency of insulin, the hormone that reduces blood glucose levels." (PMID 39552817, 2024). "The GoCARB system exemplifies how AI can assist individuals with type 1 diabetes in carbohydrate counting, using computer vision to automate the estimation process using smartphones, hence aiding in optimal insulin dosage estimations." (PMID 39608003, 2024). "Clinicians must be mindful of comorbidities, and their treatments, which can contribute to type 1 diabetes management complexity, such as emergency management when insulin pump delivery interruption occurs." (PMID 39138689, 2024). "The current approach to insulin therapy for type 1 diabetes involves either injecting insulin multiple times a day or infusing insulin continuously under the skin using an artificial pancreatic insulin pump." (PMID 38384620, 2024). "Here, we present a 22-year-old male who was diagnosed with type 1 diabetes at the age of 4 and received treatment with basal-bolus insulin therapy." (PMID 39171059, 2024). "Given this scenario, we tested the potential of insulin therapy as a cardiovascular neuromodulator in a model of type 1 diabetes." (PMID 38794147, 2024). "The DIAMOND study was a large RCT involving people with type 1 diabetes (aged 26–79 years) treated with insulin multiple daily injections that compared CGM with blood glucose monitoring." (PMID 39138689, 2024). "The SAC was applied to optimize insulin dosing in a closed-loop system designed for type 1 diabetes management." (PMID 39335656, 2024). "In the Standards of Care by the American Diabetes Association (ADA), metformin is also considered in paragraph “Non insulin treatment for type 1 diabetes”." (PMID 38610965, 2024). "Continuous glucose monitoring (CGM) and continuous subcutaneous insulin infusions (CSIIs) are the current standard treatment devices for type 1 diabetes (T1D) management." (PMID 39622650, 2024). "Type 1 diabetes involves immune-mediated destruction of insulin-producing beta cells, with eosinophils potentially playing a significant role." (PMID 39749265, 2024). "For example, type 1 diabetes mellitus (T1D) poses a greater risk of excessive weight gain in girls during puberty that can exacerbate an insulin resistance resulting from the prior destruction of insulin-producing cells in the pancreas." (PMID 39457311, 2024). "Type 1 diabetes (T1D) is an autoimmune disease that develops when T cells destroy the insulin-producing beta cells that reside in the pancreatic islets." (PMID 39554513, 2024). "Long-acting basal insulin provides basal support for patients with type 1 diabetes, which is an indispensable component of basal-bolus therapy." (PMID 39629047, 2024). "Type 1 diabetes (T1D) results from the autoimmune destruction of pancreatic-islet insulin-secreting beta cells." (PMID 39252097, 2024).
type 1 diabetes (continued). "Most recently, the use of Medtronic’s (Minneapolis, Minnesota) MiniMed 780G system was shown in the Closed-l oop Insulin Delivery in Pregnant Women With Type 1 Diabetes (CRISTAL; C linicalTrials." (PMID 39526053, 2024). "We determined factors associated with BHB changes from baseline (ΔBHB) and diabetic ketoacidosis (DKA) in patients with type 1 diabetes (T1D) receiving sotagliflozin as an insulin adjunct." (PMID 38441906, 2024). "Further improvements in maternal glucose levels and reductions in complications attributed to maternal hyperglycaemia will require more physiological approaches, including glucose responsive insulin replacement therapy in type 1 diabetes pregnancy." (PMID 38967667, 2024). "According to recent research, EVs are crucial in the transfer of autoantigenic peptides from β cells that produce insulin during the onset of type 1 diabetes (T1DM)." (PMID 38167116, 2024). "Type 1 diabetes mellitus (T1DM) is an autoimmune disease caused by the destruction of pancreatic beta cells, resulting in insufficient production of insulin." (PMID 39420935, 2024). "A network meta-analysis of 23 randomized controlled trials (n = 5151 type 1 diabetes patients) showed a decrease in body weight of 5.1 kg in the insulin + exenatide group compared with the insulin group." (PMID 39273299, 2024). "Re-framing type 1 diabetes care through open-source automated insulin delivery: ‘The (expert) patient will see you now, doctor." (PMID 39196351, 2024). "Real-world evidence on clinical outcomes of people with type 1 diabetes using open-source and commercial automated insulin dosing systems: a systematic review." (PMID 39196351, 2024). "Lu and colleagues performed a meta-analysis of 10 studies, concluding that the combination of SGLT-2 inhibitors with insulin treatment was beneficial in people with type 1 diabetes." (PMID 39598003, 2024). "Hussain S, Lal RA, Braune K. Open-source automated insulin delivery in type 1 diabetes—the evidence is out there." (PMID 39196351, 2024). "As histological studies show that some insulin positive cells are present in most subjects with type 1 diabetes, one can expect detectable circulating C-peptide in the majority of subjects as long as the C-peptide assay is sensitive enough." (PMID 38446636, 2024). "Type 1 diabetes (T1D) is a chronic metabolic disorder characterized by the inability to produce insulin." (PMID 39594662, 2024). "In recent years, clinical trials have been conducted that added SGLT-2 inhibitors to insulin therapy in people with type 1 diabetes." (PMID 39598003, 2024). "Type-I Diabetes (TID) is a disorder of the endocrine system, which is characterized by the degeneration of the insulin-generating pancreatic T-cells caused by an autoimmune attack or genetic predisposition." (PMID 39602484, 2024). "Globally, Type 1 diabetes is rare, typically emerging in childhood or early adolescence but can appear at any age, requiring lifelong insulin therapy to maintain blood sugar levels." (PMID 39777222, 2024). "Type 1 diabetes (T1D) is a chronic autoimmune condition characterized by the destruction of insulin-producing beta cells in the pancreas, leading to an absolute deficiency of insulin." (PMID 39246894, 2024). "Insulin-dependent diabetes, also known as type 1 diabetes, is a chronic autoimmune disorder in which the body's immune system attacks and destroys the pancreas's insulin-producing beta cells." (PMID 38312584, 2024). "Type 1 diabetes (T1D) results from progressive autoimmune-mediated destruction of insulin-producing beta-cells in pancreatic islets." (PMID 38150393, 2024). "Type 1 diabetes is a chronic autoimmune disease affecting beta cell function in islets of the pancreas leading to defective insulin production and uncontrolled glucose blood sugar levels." (PMID 39658052, 2024). "Type 1 diabetes requires lifelong insulin due to autoimmune destruction of insulin-producing cells, whereas Type 2 involves insulin resistance." (PMID 38499620, 2024).
type 1 diabetes (continued). "Clinical trials are planned for 2024 under the registration ‹Amr Ahmed, Maher M. Akl, Semaglutide GLP1 Agonists with Degludec Basal-bolus Insulin in Early Type 1 Diabetes to Basalbolus› (ClinicalTrials.gov Identifier NCT06057077)." (PMID 39206389, 2024). "Defects in nutrient regulation of insulin secretion, resulting from the lack of pancreatic enzymes and resistance to the cellular actions of insulin, are key to the development of non-insulin-dependent diabetes." (PMID 39596226, 2024). "Type 1 diabetes (T1D) is an autoimmune condition in which insulin-secreting beta cells of the pancreas are affected, resulting in hyperglycemia." (PMID 39436890, 2024). "For comparison the average carbohydrate intake in an adult population of people with insulin-pump-treated type 1 diabetes in the United Kingdom has been shown to be 166 g per day." (PMID 38257092, 2024). "Insulin gene expression is increased in adipocytes differentiated from ADSCs, which is crucial for the treatment of type I diabetes." (PMID 38388551, 2024). "Such a relationship was also observed among breastfeeding women with type 1 diabetes, in whom insulin is exogenous in origin." (PMID 39459341, 2024). "Caregivers provided the following data: sex, age, type and dose of insulin, age at onset of type 1 diabetes, and level of physical activity." (PMID 38529360, 2024). "For example, a reinforcement learning (RL) algorithm was developed to aid in determining the optimal dosage of long-acting insulin for individuals diagnosed with type 1 diabetes, utilizing clinical data." (PMID 37971630, 2024). "For type 1 diabetes, meticulous control of glucose values is vital due to the reliance on insulin administration." (PMID 39000969, 2024). "Insulin therapy applied was by ICT in all three patients with known type 1 diabetes and all controlled their blood sugar by self-monitoring of blood glucose, none used sensor based glucose monitoring." (PMID 38958733, 2024). "Type 1 diabetes (T1D) results from the autoimmune T-cell-mediated destruction of pancreatic beta cells leading to insufficient insulin secretion." (PMID 38397298, 2024). "This is consistent with the clinical findings in type I diabetes patients whose plasma TG was basically normal as long as insulin was given adequately to control blood glucose." (PMID 39529532, 2024). "Retrospective comparison of commercially available automated insulin delivery with open-source automated insulin delivery systems in type 1 diabetes." (PMID 39196351, 2024). "Type 1 diabetes (T1D) becomes a chronic disease that requires a daily administration of insulin and continuous self-monitoring." (PMID 39337217, 2024). "Apelin stimulates insulin secretion while significantly improving the pancreatic islet cell mass and β-cell insulin in Akita mice, which is a model used for the study of diabetes type 1." (PMID 39457235, 2024). "They found that APS-1 significantly reduced insulin levels in type 1 diabetic (T1D) mice and improved the intestinal barrier function by regulating the expression of ZO-1, Occludin, and Claudin-1." (PMID 39215362, 2024). "Islet transplantation is a promising treatment for type 1 diabetes that aims to restore insulin production and improve glucose control, but long-term graft survival remains a challenge due to immune rejection." (PMID 39267737, 2024). "Type 1 diabetes (T1D) is a chronic condition in which the body produces too little insulin, a hormone needed to regulate blood glucose." (PMID 39654139, 2024). "Adolescents with type 1 diabetes, an autoimmune disease that destroys insulin-producing cells in the pancreas, must engage in numerous daily health behaviors to manage their symptoms and prevent short- and long-term health complications." (PMID 38289663, 2024). "Individuals with type 1 diabetes require exogenous insulin to maintain blood glucose levels within the normal range." (PMID 38864887, 2024).
type 1 diabetes (continued). "Insulin is generally considered an anabolic agent in bone, with the insulinopenia typically seen among individuals with type 1 diabetes resulting in restricted osteoblast activity and potentially increased osteoclast activity." (PMID 38658414, 2024). "Combined with the control group’s higher glucose infusion rate throughout the study, this is indicative of reduced insulin sensitivity in the type 1 diabetes group, which is a well-known phenomenon, as shown in other studies." (PMID 38427076, 2024). "When the body is unable to produce enough insulin, type 1 diabetes develops, requiring lifelong insulin administration." (PMID 38465169, 2024). "For example, Cxcl12 supports β cell survival in a mouse model of type 1 diabetes and recruits macrophages to promote β cell regeneration after damage, while IL-6 has been shown to directly enhance insulin secretion." (PMID 38885342, 2024). "Although there is a large body of evidence demonstrating the efficacy of insulin pump therapy among younger adults with type 1 diabetes, evidence among older people is limited." (PMID 39138689, 2024). "Eighty percent had type 1 diabetes, and common precipitating factors for admission included infection and poor adherence to insulin treatment." (PMID 38523875, 2024). "Thereby, the severity of diabetic ketoacidosis in children with new-onset type 1 diabetes was inversely correlated with insulin sensitivity." (PMID 39519472, 2024). "Type 1 diabetes (T1D) is an autoimmune disease that results from the destruction of insulin-producing beta cells in the pancreas by infiltrating immune cells, including CD4+ and CD8+ T cells and macrophages." (PMID 38490439, 2024). "This is particularly evident in Type 1 diabetes where insulin delivery mechanisms have evolved exponentially into highly complex and effective glucose sensing and insulin pump therapy techniques." (PMID 39211732, 2024). "Type 1 diabetes (T1D) is an autoimmune disorder characterized by the destruction of insulin-producing β-cells." (PMID 38994961, 2024). "The autoimmune system attacks the pancreatic islet's insulin-producing beta cells, leading to an acute reduction in insulin secretion, known as Type 1 diabetes." (PMID 39371721, 2024). "A comparison of the usage of an open-source automated insulin delivery system and the MiniMed TM TM 780 G system in children and adolescents with type 1 diabetes in real-world settings: the AWeSoMe study group." (PMID 39196351, 2024). "It has been reported that a single course of treatment with anti-CD3 mAb, hOKT3gamma1(Ala-Ala), can help preserve insulin production in new-onset type 1 diabetes patients for longer than 1 year after administration." (PMID 39390211, 2024). "Type 1 diabetes (T1D) is an autoimmune disease resulting from T cell-mediated destruction of the insulin-producing β cells." (PMID 38317106, 2024). "In recent years, CGM systems have become the standard of care in type 1 diabetes in several countries, especially among children, adolescents, and young adults, being successfully used in insulin-treated type 2 diabetes." (PMID 39376804, 2024). "Type 1 diabetes is a chronic metabolic disorder characterized by the destruction of insulin-secreting beta cells in the pancreatic islets." (PMID 38786050, 2024). "Type 1 diabetes (T1D) is one of childhood’s most common chronic diseases, resulting from an immune attack to the insulin-producing beta cells of the pancreas, leading to altered blood glucose levels." (PMID 38397555, 2024). "Nwosu studied the effect of adjunctive ergocalciferol on residual β-cell function and partial clinical remission in youth with newly diagnosed type 1 diabetes maintained on a standardized insulin treatment for a 12-month period." (PMID 38613075, 2024). "Children and adolescents with type 1 diabetes require frequent outpatient evaluation to assess glucose trends, modify insulin doses, and screen for comorbidities." (PMID 39353188, 2024).